IL10 (interleukin 10)
Diseases named in the same sentence as IL10 in open-access papers (continued):
Sharing a sentence is not in itself a finding about the gene and the disease.
osteoporosis (35 papers, 2007 to 2025). A condition of reduced bone mass, with decreased cortical thickness and a decrease in the number and size of the trabeculae of cancellous bone (but normal chemical composition), resulting in increased fracture incidence. "Age-associated increase in plasma TNFα and IL-10 has been associated with decreased bone mineral density and increased rates of osteoporosis; elevated plasma TNFα is now an established biomarker of frailty in older adults." (PMID 38560342, 2024). "Increased concentrations of the inflammatory factors IL-6, IL-10, IL-12p70, IL-17, and IL-23 were associated with a greater risk of osteoporosis." (PMID 39039571, 2024). "Studies in mouse models have shown that IL-10 deficiency accelerates osteoporosis development and increases bone resorption." (PMID 39200293, 2024). "Recently, we for the first time reported that Bregs possess strong osteo-protective potential in an IL-10-dependent manner, and any decrease in the frequencies of Bregs was directly linked with the pathophysiology of osteoporosis." (PMID 35693779, 2022). "We aim to identify the effects of the anti-inflammatory TGF-β1- and IL-10-specific single-nucleotide polymorphism (SNP) combination on the risk for osteoporosis." (PMID 34207210, 2021). "It has also been reported that numerical defect in the Tregs population along with its efficacy to produce IL-10 cytokine results in the development of various inflammatory bone loss conditions, including osteoporosis." (PMID 34276682, 2021). "In the current study, we aimed to investigate the possible pathogenic role of IL-17A and IL-10 bone-protecting role in osteoporosis." (PMID 27999647, 2016). "Clinical studies back up the theoretical importance of this work: an IL-10 promoter gene polymorphism has been found that is associated with reduced bone mineral density and predisposes women to osteoporosis at the lumbar spine." (PMID 17239241, 2007). "In vitro and in vivo studies confirm the importance of this cytokine in bone metabolism, for instance IL-10-deficient mice develop the hallmarks of osteoporosis." (PMID 17239241, 2007). "According to the sensitivity analysis, a higher energy-adjusted DII score was positively associated with osteoporosis risk (Ptrend=0.008), and elevated levels of IL-6, IL-10, IL-12p70, IL-17, and IL-23 were also associated with increased osteoporosis risk (P < 0.05)." (PMID 39039571, 2024). "For instance, it was demonstrated that patients with herpes zoster infections presented with a 4.55-fold greater risk of osteoporosis, as associated with significantly high levels of interleukin (IL)-1b, IL-6, IL-8, IL-10, and tumor necrosis factor-alpha (TNF-α)." (PMID 37113002, 2023). "The femoral neck T-score of female subjects with both polymorphisms of the TGF-β1 SNP (−509 C/C) and IL-10 SNP (+1927 C/C) genotypes was 1.1666 higher than those in any other group (p < 0.05), which means these genotypes had a greater tendency to prevent osteoporosis." (PMID 34207210, 2021). "Moreover, the significance of IL-10 is further highlighted in IL-10 deficient mice in which all the hallmarks of osteoporosis i.e. decreased bone mass, enhanced mechanical fragility, and reduced bone formation was observed." (PMID 34276682, 2021). "Moreover, the femoral neck T-score of female subjects with both polymorphisms of the TGF-β1 (−509 C/C) and IL-10 (+1927 C/C) genotypes showed the greatest tendency to prevent osteoporosis compared with those of all other groups." (PMID 34207210, 2021). "The polymorphic genotype of the anti-inflammatory IL-10 gene could affect protein expression and activity, therefore shifting the balance between bone formation and resorption and increasing the subsequent risk of osteoporosis." (PMID 34207210, 2021).
osteoporosis (continued). "Furthermore, this finding is obviously opposite to a large number of animal studies which indicated the double role for IL-10, anti-osteoclastogenesis and pro- osteoblastogenesis in bone protection if we assumed a pathogenic role for this cytokine in osteoporosis." (PMID 27999647, 2016). "IL-10 is a cytokine that exerts a significant impact on bone metabolism, particularly in osteoporosis." (PMID 39200293, 2024). "Particularly, the immunomodulatory effects of IL-10 can regulate inflammatory responses in osteoporosis pathogenesis, affecting bone health." (PMID 39200293, 2024). "In the osteoporosis model of postmenopausal mice, serum IL-10 cytokine levels were significantly reduced." (PMID 38892016, 2024). "In OVX mice with osteoporosis, the number of regulatory B (B10) cells that produce IL-10 decreased and the number of IL-17-producing Th17 cells increased compared with control mice." (PMID 37475866, 2023). "Meanwhile, differences of IL-10 in osteopenia group versus osteoporosis group, and differences of TNF-α in control group versus osteopenia group were still significant." (PMID 36032115, 2022). "The results in this study showed that the level of the anti-inflammatory factor IL-10 was significantly lower in the osteoporosis group than in the control and osteopenia groups." (PMID 36032115, 2022). "We also found that the serum level of IL-10 in the osteoporosis group was significantly lower than that in the control group and osteopenia group, while TNF-α was significantly higher in the osteoporosis group than that in the control group (p < 0.05)." (PMID 36032115, 2022). "In IL-10 knockout mice, the hallmarks of osteoporosis can be observed, including an increased level of RANKL and osteoprotegerin, promoted bone resorption, reduced bone formation and altered trabecular structure." (PMID 34207210, 2021). "In addition, mounting studies have shown that the presence of the C allele at position—597 decreased the frequency of the G allele at position—1082, or a polymorphism of the C/C genotype at position—627 in the IL-10 promoter may constitute a risk for the development of osteoporosis." (PMID 34207210, 2021). "We investigated and analyzed the relationships between three TGF-β1 SNPs (−509C/T, +869 T/C and +29T/C), one IL-10 SNP (+1927A/C) and the level of bone mineral density (BMD), as well as the risk of osteoporosis in Taiwanese osteoporotic patients." (PMID 34207210, 2021). "On the contrary, regulatory cytokines, such as IL-10, and Th2 cytokines, such as IL-4, exert a prevalent bone anabolic action so as to be regarded as protective against osteoporosis." (PMID 30846811, 2019). "To interpret this new finding, we supposed that in compensation to chronic inflammation existed in osteoporosis subjects IL-10 synthesizing increased." (PMID 27999647, 2016). "As far as we know, this is the first study to show IL-10 expression in periodontal tissue in an animal osteoporosis model." (PMID 24683547, 2014). "Therefore, evaluating IL-10 as a potential therapeutic target in understanding and treating bone diseases such as osteoporosis is of great importance." (PMID 39200293, 2024). "The levels of IL-10 were substantially lower in osteoporosis patients than in healthy individuals." (PMID 37475866, 2023). "Conversely, the levels of IL-4 and IL-10 were lower in RA patients with osteoporosis." (PMID 37238933, 2023). "Besides, after taking time after menopause, age, estrogen and BMI as covariates together, the difference of IL-10 between the osteopenia group and the osteoporosis group was still significant." (PMID 36032115, 2022). "The authors also suggested that a combination of DAS28 (a disease activity score), IL-4, IL-10, and IL-17 could predict the incidence of osteoporosis in RA." (PMID 35955873, 2022).
osteoporosis (continued). "In the beginning of 2020, our group also highlighted the probable contribution of IL-10 producing regulatory B cells in the case of osteoporosis and found that IL-10 producing Bregs are significantly reduced in the post-menopausal osteoporotic mice model (unpublished data)." (PMID 34276682, 2021). "Thus, we evaluated the patients in terms of the SNPs TGF-β1 (−509) and IL-10 (+1927), which can also represent the effects of TGF-β1 SNPs (+869 and +9) on the risk of osteoporosis at the same time." (PMID 34207210, 2021). "Thus, we evaluated the patients in terms of the SNPs, TGF-β1 SNP (−509) and IL-10 SNP (+1927), which can also simultaneously represent the effects of the TGF-β1 SNPs (+29 and +869) on the risk of osteoporosis." (PMID 34207210, 2021). "The combination of the many SNPs in the anti-inflammatory TGF-β1 and IL-10 genes may be cooperatively involved in the development of osteoporosis." (PMID 34207210, 2021). "Cytokines and chemokines such as TNF-α, CCL-2, IL-10, SERT (Serotonin Transporter) and Tph1 may be possible mediators between the GM and steroid deficiency-induced osteoporosis." (PMID 32484785, 2020). "Despite the fact that the expression levels of IL-10 and IL-17α in the colon were impacted in a way that has been shown to favor the development of osteoporosis (32, –, 34), serum levels of TNF-α and T cell populations in the bone marrow compartment were not impacted by the presence of a microbiota." (PMID 29299532, 2018). "The differences in OPG, RANKL, IL-4 and IL-10 levels we observed between CD and UC patients confirm a different pathophysiology of these two diseases and a different molecular background of coexisting osteoporosis." (PMID 27639566, 2016). "Hence, determining the correlation between serum IL-10/IL-17 and vitamin D levels can be a useful achievement in understanding immunological aspects of osteoporosis as well as for its management especially in elderly people with vitamin D supplementation." (PMID 27999647, 2016). "Although intensive studies have done to investigate effects of many cytokines on BMD and/or osteoporosis, the cytokines involved are still largely unknown, whether IL10 is responsible for the induced osteoclastogenesis in this study still need to be confirmed." (PMID 27711227, 2016). "The low level of IL-10 results in the insufficient inhibition of the proinflammatory cytokines and collagenase, which may have an impact on osteoporosis development." (PMID 24696846, 2014). "Recent studies have indicated that the polymorphisms of IL-10 gene, which may affect IL-10 production, are associated with reduced bone mineral density (BMD) in postmenopausal women who were prone to suffered from osteoporosis." (PMID 24696846, 2014). "However, IL-10 levels increased in osteoporosis patients following anti-osteoporosis treatment." (PMID 37475866, 2023). "However, the biological significance of the IL-10 (+1927) polymorphism in osteoporosis has not been revealed until now." (PMID 34207210, 2021). "Analysis of spleen tissue revealed increased expression of IFN-γ and IL-10 in the ALN-administered group, consistent with the known efficacy of osteoporosis treatments." (PMID 41007168, 2025). "Elderly male patients with osteoporosis had higher expression of RANKL/OPG, TNF-α, IL-6, and lower expression of IFN-γ and IL-10." (PMID 38817601, 2024). "After taking time after menopause, age, estrogen and BMI as covariates separately, the differences of IL-10 disappeared while the differences of TNF-α became significant between the control group and the osteoporosis group." (PMID 36032115, 2022). "Based on these findings, we hypothesized that the spleen plays an important role in osteoporosis and thus analyzed IFN-γ and IL-10 expression." (PMID 41007168, 2025). "Serum levels of TNF-α, IL-6, and IL-17 were higher and levels of IL-4 and IL-10 were lower in RA patients when compared to those without osteoporosis." (PMID 35955873, 2022).
osteoporosis (continued). "Lachnoclostridium had a significantly negative correlation with serum IL-10 and estrogen levels, whereas Bifidobacterium spp., which significantly increased in the osteoporosis group, had a significantly positive correlation with lumbar spine BMD (LS BMD)." (PMID 36032115, 2022). "The expression of IL-1β, IL-6, IL-10, TNF-α, OPG, RANKL, and MMP-8 in periodontal tissues, with or without osteoporosis, was analyzed using enzyme-linked immunosorbent assays and immunohistochemistry." (PMID 24683547, 2014). "Furthermore, it has been observed that Th2 dominance is related with senile osteoporosis, implying that Th2-type cytokines such as IL-10, IL-6, IL-5, and IL-4 levels rose while Th1-type cytokines such as IL-2,IFN-γ and TNF-α reduced in patients suffering from senile osteoporosis." (PMID 38461235, 2024). "Additionally, Fusicatenibacter spp., which were significantly increased in the osteoporosis group, were found to have a significantly positive correlation with the time after menopause but a negative correlation with serum IL-10 and estrogen levels." (PMID 36032115, 2022). "Animal studies have shown that a lack of IL-10 expression decreases femoral BMD, increases bone fragility and inhibits bone resorption, eventually leading to osteoporosis." (PMID 34207210, 2021). "For instance, the receptors of TGF-β and IL-10 are widely expressed in non-immune cells and especially TGF-β signaling can trigger many age-related degenerative changes, e.g., cellular senescence, fibrosis, osteoporosis, and ECM disruption." (PMID 33025106, 2021).
pneumococcal infection (35 papers, 2010 to 2025). Infections with bacteria of the species streptococcus pneumoniae. "Low levels of IL-10 are known to be associated with high levels of INF-γ during pneumococcal infection, leading to exacerbated inflammation." (PMID 34458307, 2021). "On the other hand, PG05 treatment induced the greatest increase of IL-10 in BAL after pneumococcal infection, which could be associated to the reduction of tissue damage and recruitment of neutrophils to the airways observed in this group." (PMID 29518131, 2018). "Following Streptococcus pneumoniae infection, aged mice also exhibit exacerbated inflammation due to reduced IL-10 production and increased chemokine release." (PMID 40559147, 2025). "The resistance to the infection, the lung damage, and the levels of respiratory IFNs and IL-10 were determined and compared with those obtained from experiments in which pneumococcal infection was produced 5 days after poly(I:C) stimulation." (PMID 39766307, 2024). "During Streptococcus pneumoniae infection, infiltration of neutrophils into the lungs serve as a cellular source of IL-10 and mediate an effective Th2-mediated response immune response necessary for host survival." (PMID 39602398, 2024). "Bordatella-induced IL-10 suppresses neutrophil infiltration, as we find during pneumococcal infection." (PMID 37381945, 2024). "Together, these data implicate S. pneumoniae-induced IL-10 in the restraint of neutrophil-mediated protection against pneumococcal infection." (PMID 37381945, 2024). "During pneumococcal infection in mice, IL-10 production is required to temper an excessive lung injury and to improve survival, while IL-27 in combination with IL-6 are involved in the ability of AMs to ty to promote Treg cell responses." (PMID 37958756, 2023). "In this context, future studies will be required to investigate a potential immunomodulatory effect of trained IL-10 production during pneumococcal infection." (PMID 35856089, 2022). "Serpinb2−/− mice exhibited increased C5a levels, but decreased IL-10 levels in the brain during pneumococcal infection." (PMID 36309755, 2022). "Acute pneumococcal infection further increased the expression of IL-10 and ARG1 in the lungs of HDM-exposed mice." (PMID 35273509, 2022). "IL-10 during Streptococcus pneumoniae infection was produced to modulate the inflammatory response and the immune homeostasis." (PMID 34959964, 2021). "In this sense, nasal administration of immunobiotics or PG05 is responsible for increasing IL-10 levels in bronchoalveolar lavage of malnourished mice after pneumococcal infection." (PMID 34458307, 2021). "IL-10 is known to modulate the immune response induced after a pneumococcal infection, limiting the inflammatory immune response and stimulating antibody production in both children and mice." (PMID 34458307, 2021). "Namely, IL-10 production during pneumococcal infection, a critical anti-inflammatory cytokine necessary to control excessive lung inflammation, is reduced by protein deprivation." (PMID 34458307, 2021). "In contrast, anti-IL-10 monoclonal antibody treatment in Py+Sp co-infected mice was sufficient to significantly reduce the severity of Pneumococcal infection compared to control IgG treated Py+Sp mice." (PMID 32714882, 2020). "The levels of BAL IFN-β, IFN-γ, and IL-10 were also determined after the secondary pneumococcal infection in infant mice treated with liposomes." (PMID 32660087, 2020). "Of interest, in a murine model of sub-lethal Streptococcus pneumonia infection, NK cells produced IL10, which restricted host protection, indicating again the immunoregulatory role of NK cells." (PMID 33120910, 2020). "In this regard, IL10 production after Streptococcus pneumoniae infection is important to avoid excessive inflammation of tissues and to improve host survival, even though there is lower bacterial dissemination in the absence of this cytokine." (PMID 33120910, 2020).